GATA4 (GATA binding protein 4)
Description:
Transcriptional activator that binds to the consensus sequence 5'-AGATAG-3' and plays a key role in cardiac development and function. In cooperation with TBX5, it binds to cardiac super-enhancers and promotes cardiomyocyte gene expression, while it down-regulates endocardial and endothelial gene expression. Involved in bone morphogenetic protein (BMP)-mediated induction of cardiac-specific gene expression. Binds to BMP response element (BMPRE) DNA sequences within cardiac activating regions (By similarity). Acts as a transcriptional activator of ANF in cooperation with NKX2-5 (By similarity). Promotes cardiac myocyte enlargement. Required during testicular development. May play a role in sphingolipid signaling by regulating the expression of sphingosine-1-phosphate degrading enzyme, sphingosine-1-phosphate lyase.
Synonyms: ASD2; TACHD; TOF; VSD1
Tractability: No criterion of Open Targets' tractability assessment is met for any kind of drug.
Target class: Transcription factor
Gene: Protein-coding gene on chromosome 8 (11,676,785 to 11,760,002, forward strand). Ensembl gene ENSG00000136574.
Subcellular location: Nucleus
Subcellular location (Human Protein Atlas): Nuclear bodies
Pathways (Reactome):
Developmental Biology: Cardiogenesis; Developmental Lineage of Multipotent Pancreatic Progenitor Cells; Developmental Lineage of Pancreatic Acinar Cells; Developmental Lineage of Pancreatic Ductal Cells; Formation of definitive endoderm; Formation of lateral plate mesoderm; Transcriptional regulation of testis differentiation
Gene expression (Transcription): YAP1- and WWTR1 (TAZ)-stimulated gene expression
Hemostasis: Factors involved in megakaryocyte development and platelet production
Metabolism of proteins: Synthesis, secretion, and inactivation of Glucose-dependent Insulinotropic Polypeptide (GIP)
Muscle contraction: Physiological factors
Gene Ontology:
Molecular function: co-SMAD binding; DNA binding; DNA-binding transcription activator activity; DNA-binding transcription activator activity, RNA polymerase II-specific; DNA-binding transcription factor activity; protein binding; RNA polymerase II cis-regulatory region sequence-specific DNA binding; RNA polymerase II transcription regulatory region sequence-specific DNA binding; RNA polymerase II-specific DNA-binding transcription factor binding; sequence-specific double-stranded DNA binding; transcription cis-regulatory region binding; DNA-binding transcription factor activity, RNA polymerase II-specific; sequence-specific DNA binding; chromatin binding; cis-regulatory region sequence-specific DNA binding; DNA-binding transcription factor binding; NFAT protein binding; protein kinase binding; transcription coactivator binding; zinc ion binding
Biological process: aortic valve morphogenesis; atrial septum morphogenesis; atrial septum secundum morphogenesis; endocardial cushion development; intestinal epithelial cell differentiation; male gonad development; positive regulation of DNA-templated transcription; positive regulation of transcription by RNA polymerase II; response to xenobiotic stimulus; atrial septum primum morphogenesis; atrioventricular canal development; atrioventricular node development; atrioventricular valve formation; cardiac muscle tissue regeneration; cardiac right ventricle morphogenesis; cardiac ventricle morphogenesis; cell fate commitment; cell-cell signaling; embryonic foregut morphogenesis; embryonic heart tube anterior/posterior pattern specification; endoderm development; heart looping; negative regulation of apoptotic signaling pathway; negative regulation of cardiac muscle cell apoptotic process; negative regulation of oxidative stress-induced intrinsic apoptotic signaling pathway; and 29 more
Cellular component: nuclear body; nucleus; RNA polymerase II transcription regulator complex; chromatin; nucleoplasm
Genetic constraint (gnomAD): Loss-of-function variants: 7 observed, 28.07 expected, observed/expected ratio (o/e) 0.25, 90% interval 0.14 to 0.47. The synonymous counts are far from expectation, so gnomAD's model fits this gene poorly and the ratio says little. Missense variants: 647 observed, 553.83 expected, observed/expected ratio (o/e) 1.17, 90% interval 1.09 to 1.25. Synonymous variants: 372 observed, 246.03 expected, observed/expected ratio (o/e) 1.51, 90% interval 1.39 to 1.65.
Gene-disease validity (ClinGen):
ClinGen rates the evidence that GATA4 causes each of these diseases.
structural congenital heart disease, multiple types - GATA4 (autosomal dominant): Definitive. Any congenital heart disease in which the cause of the disease is a mutation in the GATA4 gene.
Homologues: Orthologues: chimpanzee GATA4 (100% identical), macaque GATA4 (98% identical), rabbit GATA4 (95% identical), dog GATA4 (95% identical), pig GATA4 (94% identical), rat Gata4 (93% identical), mouse Gata4 (93% identical), tropical clawed frog gata4 (62% identical), guinea pig Gata4 (49% identical), zebrafish gata4 (48% identical), Drosophila melanogaster GATAe (27% identical), Caenorhabditis elegans elt-2 (14% identical), and 1 more. Paralogues in human: GATA6 (48% identical), GATA5 (42% identical), GATA2 (33% identical), GATA3 (32% identical), GATA1 (28% identical), TRPS1 (19% identical), ZGLP1 (7% identical).
Diseases named in the same sentence as GATA4 in open-access papers:
GATA4 is named in the same sentence as 279 diseases in open-access papers, as found by Europe PMC text mining. Sharing a sentence is not in itself a finding about the gene and the disease. The quoted sentences say what the papers report.
cardiac hypertrophy (164 papers, 2010 to 2026). "GATA4, as a transcriptional regulator, modulates the expression of a broad spectrum of cardiac genes, including those associated with cardiac hypertrophy, such as ANP, BNP and MHC." (PMID 40753540, 2025). "Various stimuli associated with cardiac hypertrophy and heart failure enhance GATA4 transcriptional activity through phosphorylation." (PMID 40463063, 2025). "GATA4 has been well‐established as a direct transcriptional activator of hallmark cardiac hypertrophy markers, including ANP, BNP, and β‐MHC." (PMID 41143277, 2025). "We examined activation of transcription factor GATA-4, which is implicated in the development of cardiac hypertrophy, following the administration of DOX." (PMID 39408900, 2024). "Overexpression of GATA-4 leads to myocardial hypertrophy in vivo by regulating the expression of various genes associated with cardiac hypertrophy and heart failure, including ANP, BNP, α-myosin heavy chain (α-MHC), and β-MHC." (PMID 39408900, 2024). "Expression of a dominant negative GATA4 by a GATA4 engrailed repressor fusion-encoding adenovirus ameliorates phenylephrine-induced cardiac hypertrophy and remodeling in NRVMs." (PMID 35185581, 2022). "On the other hand, it has been shown that overexpression of ERRγ, a member of the ERR family, in cardiomyocytes causes cardiac hypertrophy via the GATA-binding protein 4 (GATA4)." (PMID 35055179, 2022). "The regulatory assembly of cardiac hypertrophy further employs zinc finger-containing transcription factor GATA4 which is a crucial component implicated in hypertrophic growth and heart development whose elevated levels were also associated with diabetes." (PMID 36568083, 2022). "The involvement of HATs and HDACs in cardiac hypertrophy and fibrosis is explained by their ability to regulate histone acetylation at the promoter region of Gata4 and Mef2c and to associate with these transcription factors." (PMID 31936461, 2020). "Previously, NFATc3 and GATA4 transgenic overexpression studies reveal its significant association in the development of myocardial hypertrophy." (PMID 31211784, 2019). "Previous researches have implicated GATA-4 and NFATc3 as primary transcription factors in cardiac hypertrophy responses." (PMID 31480672, 2019). "Cardiac hypertrophy‐associated upregulation of the transcription factors GATA4 and Sp1 and activation of extracellular signal‐regulated kinase 1/2 were also negated by these drugs." (PMID 30256522, 2018). "Cardiac specific GATA4 knockout(loss of function) are more resistant to development of cardiac hypertrophy and HF after agonist stimulation or pressure overload." (PMID 27893819, 2016). "This activation evokes a dephosphorylation of NFATc3 within the cytoplasm, which translocates to the nucleus, where it associates with transcription factor like GATA-4, to regulate the cardiac genes and develop cardiac hypertrophy." (PMID 27880816, 2016). "GATA4 is a zinc finger, containing transcription factor that plays key roles in promoting heart growth and regulating cardiac hypertrophy, and is associated with multiple hypertrophic signaling pathways, such as ERK1/2, p38, Akt, and CnA/NFATc3." (PMID 25093027, 2014). "Cardiac hypertrophy is mediated by three main transcription factors Mef2, NF-AT, and Gata4, and all of these genes were linked with changes in DNA methylation in our analysis." (PMID 24475304, 2014). "Notably, dysregulation of GATA4 has been implicated in the progression of cardiac hypertrophy and heart failure, underscoring its potential as a therapeutic target in cardiovascular medicine." (PMID 41143277, 2025). "Furthermore, cardiomyocyte-specific GATA4-deficient or transgenic mice has revealed its requirement for the development of cardiac hypertrophy." (PMID 37219631, 2023).
cardiac hypertrophy (continued). "Furthermore, it has been reported that loss of TFEB leads to cardiac hypertrophy by blocking autophagic degradation of GATA4, a transcription factor responsible for the upregulation of several cardiac-specific fetal genes involved in cardiomyocyte growth." (PMID 37188688, 2023). "In addition, a recent study has shown that cardiac-specific overexpression of Fgf16 via AAV9 in Gata4-deficient hearts rescued cryoinjury-induced cardiac hypertrophy, promoted cardiomyocyte replication and improved heart function after injury." (PMID 36399125, 2022). "However, overexpression of GATA4 is also associated with decompensated cardiac hypertrophy, as it occurs in neuroendocrine overactivation-induced HF." (PMID 33869297, 2021). "Therefore, we also deduced the nuclear enrichment of cardiac hypertrophy associated transcription factors and noticed there was increased nuclear enrichment of GATA4 and NFATc3 with β-catenin upon Ang-II treatment in a dose-dependent assessment." (PMID 31480672, 2019). "However, several other studies have implicated the transcription factors NFATc3 and GATA4 in development of pathological cardiac hypertrophy." (PMID 31480672, 2019). "Our study identifies MARCH5 as a novel regulatory component in myocardial hypertrophy through its modulation of the Akt/mTOR/Gsk‐3β/GATA4 signalling axis." (PMID 40753540, 2025). "In conclusion, our study provides novel insights into the epigenetic regulation of cardiac hypertrophy through H3K18la lactylation‐mediated activation of GATA4 signaling pathways." (PMID 41143277, 2025). "To further elucidate the role of Gata4 uORF in stress-induced cardiac hypertrophy, we subjected mice from three genotype groups to transverse aortic constriction (TAC)." (PMID 40463063, 2025). "To explore the molecular mechanism underlying H3K18la‐mediated hypertrophic gene expression, we investigated the interaction between H3K18la and GATA4, a key transcription factor involved in cardiac hypertrophy." (PMID 41143277, 2025). "A key mechanistic finding of our study is the interaction between H3K18la and GATA4, a crucial transcription factor known to regulate cardiac hypertrophy." (PMID 41143277, 2025). "Although the association between GATA4 and cardiovascular disease has been extensively studied, there is currently insufficient research on whether it regulates epigenetic modifications in myocardial cells, especially the role of H3K18la in myocardial hypertrophy." (PMID 41143277, 2025). "Our findings identify H3K18la lactylation as a novel epigenetic mechanism driving cardiac hypertrophy through GATA4 activation." (PMID 41143277, 2025). "The present study aimed to elucidate the role of H3K18la lactylation in cardiac hypertrophy through GATA4 signaling pathways using both in vivo and in vitro models." (PMID 41143277, 2025). "GATA4 is a transcription factor that mediates cardiac hypertrophy and is a known regulator of hypertrophic-related genes such as BNP and ANP in the heart." (PMID 40108505, 2025). "Our findings suggest that MARCH5 participates in the pathological cardiac hypertrophy by regulating the Akt/mTOR/Gsk‐3β/GATA4 pathway, positioning it as a promising therapeutic target for cardiac hypertrophy." (PMID 40753540, 2025). "Overall, our results demonstrate that H3K18la lactylation promotes cardiac hypertrophy through activation of GATA4 signaling pathways." (PMID 41143277, 2025). "Proposed model of the interaction of the H3K18la lactylation with GATA4 to promote the cardiac hypertrophy." (PMID 41143277, 2025). "In conclusion, we demonstrate that MARCH5 promotes cardiac hypertrophy through the Akt/mTOR/Gsk‐3β/GATA4 pathway." (PMID 40753540, 2025). "Mechanistic studies indicated that MARCH5 directly interacted with Akt, enhancing the phosphorylation of Akt, mTOR and Gsk3β, thereby increasing GATA4 expression and aggravating cardiac hypertrophy." (PMID 40753540, 2025).
cardiac hypertrophy (continued). "The Yi–Xin–Shu (YXS) capsule, a drug suggested by traditional Chinese medicine (TCM), is commonly applied in the treatment of cardiac hypertrophy by regulating the expression of GATA4, HDAC1, and retinoblastoma (RB) and the corresponding signalling pathway." (PMID 40660005, 2025). "In subsequent experiments, we intend to prolong the intervention period to further elucidate the role of GATA4 in myocardial hypertrophy." (PMID 41143277, 2025). "YXS inhibits the abnormally high expression of GATA4 in cardiovascular hypertrophy, which can be regulated by interactions between HDAC1 and the general control nonrepressed 5 protein (GCN5)." (PMID 40660005, 2025). "Numerous other studies have demonstrated that the calcineurin/NFAT signal and GATA-4 signaling pathway plays a pivotal role in the progression of cardiac hypertrophy." (PMID 39408900, 2024). "Since Gata4 is an essential transcription factor in the gene regulation of cardiac hypertrophy, recent research has been focused on targeting Gata4 as a modulator of post-translational modification." (PMID 39590198, 2024). "Several lines of evidence suggest the involvement of GATA4 in the development of cardiac hypertrophy." (PMID 38167208, 2024). "On the contrary, HDAC2, by binding to NFAT or GATA4, activates excessive gene expression, which has led to the development of myocardial hypertrophy." (PMID 38672493, 2024). "In the adult mouse heart, GATA4 is involved in promoting cardiac hypertrophy and maintaining cardiac function during pathological pressure overload." (PMID 39080192, 2024). "Nuclear-activated NFAT-3 interacts with the GATA-4 transcription factor to induce myocardial hypertrophy and the expression of hypertrophic response genes such as ANP and BNP." (PMID 39408900, 2024). "P300 can also form a complex with GATA4 to increase the transcriptional regulation of cardiac hypertrophy genes and promote the occurrence of myocardial hypertrophy." (PMID 38584203, 2024). "Dephosphorylated NFAT-3 further interacts with the GATA binding protein 4 (GATA-4) transcription factor, allowing translocation to the nucleus to form a complex that participates in the development of myocardial hypertrophy." (PMID 39408900, 2024). "The overexpression of neuraminidase 1 in hypertrophic cardiomyocytes and its interaction with the nuclear GATA4 gene promotes the development of cardiac hypertrophy in mice." (PMID 38672493, 2024). "Accordingly, our results suggest that TGW improves cardiac hypertrophy by regulating the calcineurin/NFAT and GATA4 pathway, which is a transcriptional regulator for the generation of cardiac hypertrophy." (PMID 39408900, 2024). "GATA4’s molecular function has been primarily studied in cardiac hypertrophy, while in cancer, it has been shown to act as a tumor suppressor in pancreatic adenocarcinoma, lung, and colorectal cancers." (PMID 39456519, 2024). "Since Gata4 is an essential transcription factor in gene regulation of cardiac hypertrophy, recent research has been focused on targeting Gata4 as a modulator of post-translational modification." (PMID 39070633, 2024). "This study investigated the protective effect of SJT on cardiac hypertrophy through the regulation of the calcineurin/NFAT/GATA4 pathway." (PMID 38137908, 2023). "GATA4, an important transcription factor related to cardiac hypertrophy, promotes cardiac hypertrophic marker proteins including ANP, BNP, and β-MHC." (PMID 38137908, 2023). "circRNA_000203 is able to worsen cardiac hypertrophy via targeting miR-26b-5p and miR-140-3p, resulting in higher Gata4 levels, a known regulator of cardiac hypertrophy." (PMID 38259314, 2023). "Next, cardiomyocyte surface area, atrial natriuretic peptide (ANP), brain natriuretic peptide (BNP), and GATA4 expressions were ascertained to validate the incidence of cardiac hypertrophy." (PMID 36875113, 2023).